ANXA4 (annexin A4)
Diseases named in the same sentence as ANXA4 in open-access papers (continued):
Sharing a sentence is not in itself a finding about the gene and the disease.
mucinous adenomas (1 paper, 2013). "Only two mucinous adenomas were examined, but both of them showed an IHC score 6 expression of ANXA4, presenting a similarity to their malignant counterpart." (PMID 24244679, 2013).
myelogenous leukemia (1 paper, 2015). "In our present study, several calcium-binding proteins were identified in doxorubicin-resistant myelogenous leukemia cells, such as sorcin, protein S100-A4, annexin A4, calreticulin, etc., indicating that metal ions such as calcium might play a pivotal role in the development of chemoresistance." (PMID 25628518, 2015).
neuroblastoma (1 paper, 2022). Neuroblastoma (NB) is the most common solid, extracranial childhood tumor. "It has been observed that the ionomycin treatment of murine neuroblastoma cells results in translocation to the cell membrane of ANX, in the following order: ANXA2, ANXA4, ANXA6, ANXA1, ANXA5." (PMID 35207075, 2022).
ovarian adenocarcinoma (1 paper, 2014). An adenocarcinoma that arises from the ovary. "We first confirmed ANXA4 expression in various ovarian adenocarcinoma cell lines." (PMID 25277200, 2014).
ovarian serous cystadenocarcinoma (1 paper, 2019). A malignant serous cystic epithelial neoplasm arising from the ovary. "The TCGA database confirmed that ANXA4 expression was downregulated in ovarian serous cystadenocarcinoma (P = 4.81E−6, fold change = − 2.019) and that ANXA13 was downregulated in malignant tumor tissues (P = 1.68E−4, fold change = − 9.347)." (PMID 31474227, 2019).
ovarian serous tumor (1 paper, 2019). A benign, borderline, or malignant epithelial tumor of the ovary characterized by the presence of neoplastic epithelial cells that, in well differentiated tumors, resemble the epithelial cells of the fallopian tube and, in poorly differentiated tumors, show anaplastic features. "Prognostic analysis suggested that ANXA2 and ANXA4 mRNA upregulation was significantly correlated with poor OS in patients with ovarian serous tumors." (PMID 31474227, 2019). "Upregulation of ANXA2, ANXA4, ANXA8, and ANXA9 mRNAs displayed significant correlations with poor OS in patients with ovarian serous tumors." (PMID 31474227, 2019).
polycystic ovary syndrome (1 paper, 2024). A disorder that manifests as multiple cysts on the ovaries. "Another systematic review, the first to combine proteomic studies of the placental biopsies of PE and polycystic ovary syndrome, found five biomarkers for PE which are common in women with PCOS, among which AnxA4 was downregulated in both groups of patients." (PMID 38495790, 2024).
preeclampsia (1 paper, 2024). Preeclampsia is a hypertensive disorder of pregnancy that is characterized by new-onset hypertension with proteinuria presenting after 20 weeks of gestation, and depending on mild or severe forms may initially present with severe headache, visual disturbances, and hyperreflexia. "Proportionately, proteomic PLCD4 (p.L696P) analyses of human placental tissues have shown that ANXA4 expression is downregulated in preeclampsia (PE) placentas and PE placenta-derived extravillous cytotrophoblasts compared with the expression in normal placentas." (PMID 39399103, 2024).
thyroid cancer (1 paper, 2023). "Several members of this family have been linked to cancer, with annexin A2 being one of the most studied annexins and a known cancer biomarker, and annexin A4 also being associated with different cancers such as colorectal, gastric, and thyroid cancer." (PMID 37833989, 2023).
cancer (49 papers, 2000 to 2025). A tumor composed of atypical neoplastic, often pleomorphic cells that invade other tissues. "ANXA4, a Ca2+-dependent membrane-binding protein modulating membrane permeability has been linked to many cancer types, however, its association with iNPH remains elusive." (PMID 37277809, 2023). "The pan-cancer analysis suggested that ANXA4 was significantly associated with prognosis and immune infiltration in various cancer types, which has the potential as a novel biomarker in cancer patients." (PMID 34540918, 2021). "Immune correlation analysis indicated that ANXA4 expression levels were associated with tumor immune infiltration in most cancer types." (PMID 34540918, 2021). "Among all the annexins, ANXA4 is associated with cell adhesion, apoptosis, carcinogenesis, and invasion of cancer cells." (PMID 34181340, 2021). "For example, the upregulation of annexin A4 as well as A7 promotes tumor progression and is associated with poor prognosis and drug resistance in multiple types of cancers including CRC, but function as tumor suppressors in other types of cancers." (PMID 28423508, 2017). "ANXA2 overexpression was positively correlated with advanced cancer phenotypes, whereas ANXA4 expression was associated with resistance to radiation with or without chemotherapy (p = 0.029)." (PMID 27402115, 2016). "Of all annexins, ANXA4 was related to the loss of cell adhesion, and play important roles in apoptosis, carcinogenesis, chemoresistance, migration and invasion of cancer cells." (PMID 27485544, 2016). "ANXA4 expression has been associated with loss of cell-to-cell adhesion, increased metastasis, and chemo-resistance, and therefore is regarded as a potential diagnostic and therapeutic marker in cancer field." (PMID 32986366, 2020). "We suggest that H. pylori-generated plasma membrane disruptions might serve as pathogenic events in H. pylori-induced carcinogenesis, and AnxA4 could be a new drug target for cancer treatment." (PMID 22949854, 2012). "In addition to its involvement in the progression of cancer, ANXA4 has also been linked to acquired chemoresistance to anticancer drugs." (PMID 22970268, 2012). "The results indicated that ANXA4 expression was significantly associated with B cell in 15 cancer types, macrophage in 17 cancer types, dendritic cell in 20 cancer types, neutrophil in 16 cancer types, CD4+ T cell in 14 cancer types, and CD8+ T cell in 16 cancer types." (PMID 34540918, 2021). "ANXA4 has been implicated in several cancers, and the current results suggest that therapy targeting ANXA4 may suppress the NF-κB signaling pathway, further reversing ANXA4 overexpression in a feedback regulatory mechanism and resulting in inhibition of tumor growth." (PMID 27491820, 2016). "An increasing number of studies have shown that ANXA4 is highly expressed in various clinical tumors and is an indicator of tumor development, invasion, chemoresistance, and poor outcomes in cancer patients." (PMID 39399103, 2024). "Results of survival analysis suggested prognostic significance of ANXA4 expression levels in diverse cancer types." (PMID 34540918, 2021). "We then combined with the GTEx database to analyze the expression differences of ANXA4 between tumor tissues and normal tissues in 27 different cancer types due to small numbers of normal tissues in TCGA." (PMID 34540918, 2021). "Third, further prospective studies on cancer patients with AF should be carried out to evaluate the efficacy of ANXA4 in reducing the incidence of AF in cancer patients." (PMID 34540918, 2021). "The expression levels of ANXA4 were markedly positively correlated with infiltrating immune cells in most cancer types, especially in LGG, LIHC, PCPG, PRAD, and THCA." (PMID 34540918, 2021).
cancer (continued). "We identified 12 genes that were significantly differentially expressed in R compared to NR patients across the three cancer types, comprising 10 downregulated genes and 2 upregulated genes (ANXA4, TMEM101)." (PMID 34921236, 2021). "We found that expression levels of ANXA4 were significantly correlated with DNA methylation in diverse cancer types, especially in BRCA, HNSC, KIRP, LIHC, PCPG, and UVM." (PMID 34540918, 2021). "Survival analysis suggested prognostic significance of ANXA4 expression levels in various cancer types." (PMID 34540918, 2021). "It is important to note that AnxA4 is highly expressed in cancer cells and that MCF-7 cells were exposed to strong injuries by laser irradiation inducing a large wound diameter (up to 3 μm) in the study cited above." (PMID 32708200, 2020). "Annexin proteins appear to be instrumental for coping with abiotic stress responses in plants, and human annexins including ANXA4, are overexpressed in various cancer types characterized by enhanced intrinsic stress." (PMID 29158488, 2017). "Annexin A4 (ANXA4), also called lipocortin IV and endonexin I, is associated with progression, invasion, migration, and drug resistance of cancers." (PMID 27402115, 2016). "As previously reported, treatment of A549 and Calu-2 cancer cells with paclitaxel induced cytosolic depletion of Annexin A4 that underwent a considerable translocation to the inner side of plasma membrane." (PMID 27166255, 2016). "A significant increase in ANXA4 expression was detected in cancer tissues compared with that in normal cervix (mean histoscores; 73 vs. 34, p < 0.001)." (PMID 27402115, 2016). "ANXA4 expression is increased in many cancer types, including cancers of renal, gastric, colonic, ovarian, and cervical origins." (PMID 27755556, 2016). "ANXA2 expression was lower in cancer tissue (p = 0.002), whereas ANXA4 staining increased significantly in cancer tissues (p < 0.001)." (PMID 27402115, 2016). "ANXA4 has been reported to be strongly expressed and involved in chemoresistance in various cancers." (PMID 25277200, 2014). "With regard to cancer, ANXA4 overexpression has been reported in various tumours, such as lung, gastric, colorectal, renal, pancreatic, ovarian and prostate cancer and is associated with tumour invasiveness, metastasis and chemoresistance." (PMID 25277200, 2014). "Although several in vitro investigations have shown ANXA4 to be involved in cancer cell proliferation, chemoresistance, and migration, these studies were generally based on its overexpression in cells other than CCC." (PMID 24244679, 2013). "There were 9 genes classified as cancer-related genes in ANXA4-overexpressing cells including 7 genes that were up-regulated in our experiments." (PMID 22970268, 2012). "From these studies, we identified 9 cancer-related genes from ANXA4 downstream signals by using the Ingenuity Pathway Analysis (IPA) database." (PMID 22970268, 2012). "Additionally, a hub immune-related gene in AF related to cancer named ANXA4 had been previously identified." (PMID 37374146, 2023). "In the present study, we found that PKM and ANXA4 were detected with SNO in human cancer tissue." (PMID 37124724, 2023). "In that case, ANXA4 could induce membrane remodeling that would promote membrane resealing, as proposed in cancer cells." (PMID 35207075, 2022). "Expression levels of ANXA4 increased in diverse cancer types." (PMID 34540918, 2021). "We then analyzed ANXA4 expression levels and found increased ANXA4 expression in diverse cancer types, indicating that ANXA4 might act as an oncogene." (PMID 34540918, 2021). "Furthermore, the correlations between immune infiltration and ANXA4 expression levels in various cancer types were calculated." (PMID 34540918, 2021). "Higher ANXA4 expression significantly decreased CD4+ Th1 cells across 30 cancer types." (PMID 34540918, 2021).
cancer (continued). "ANXA4 might play crucial roles in AF and cancer, and targeted therapy for ANXA4 might reduce the incidence of AF in cancer patients." (PMID 34540918, 2021). "Considering its role in AF and cancer, targeted therapy for ANXA4 might reduce the incidence of AF in cancer patients." (PMID 34540918, 2021). "However, the roles of ANXA4 in cancers were analyzed solely based on our bioinformatics analysis, whereas in vitro or in vivo experiments should be conducted to elucidate the molecular mechanisms of ANXA4 in different cancer types." (PMID 34540918, 2021). "Regarding human cells, the rapid recruitment of Anx in a tight structure, which may look like a cap subdomain, has been observed for AnxA5 in skeletal muscle cells and AnxA4 and AnxA6 in cancer epithelial cells." (PMID 32708200, 2020). "Also, ANXA4 has been reported to be involved in tumor spread and anti-cancer drug resistance (Mussunoor and Murray, 2008 ), and was identified as a potential biomarker for gall bladder cancer." (PMID 32986366, 2020). "Studies suggest that the expression of ANXA4 in many tumors is specific to particular pathology types and may therefore be a marker molecule for different subtypes of cancers." (PMID 29296226, 2017). "The role of ANXA4 in cancer and chemoresistance suggests that it could represent a potential therapeutic target for cancer treatment." (PMID 27491820, 2016). "Furthermore, ANXA4 has also shown to be involved in tumor dissemination and anti-cancer drug resistance." (PMID 27491820, 2016). "These functions may explain the involvement of ANXA4 in modulating drug resistance through efflux of intracellular chemotherapy drugs in cancer cells." (PMID 27402115, 2016). "While in the BSCC, ANXA4 protein showed intensively staining of the cytoplasm in cancer cell." (PMID 27485544, 2016). "From this transcriptional gene data, we show that overexpression of ANXA4 regulates genes that are known to be related to cancer, for example the activation of hyaluronan mediated motility receptor (RHAMM), AKT, and cyclin-dependent kinase 1 (CDK1) as well as the suppression of p21." (PMID 22970268, 2012). "Thus, ANXA4 might play crucial roles in AF and cancer, and targeted therapy for ANXA4 might reduce the incidence of AF in cancer patients." (PMID 37374146, 2023). "However, studies performed in cancer cells have shown that ANXA4 accumulated at the damaged area, where it may induce invagination of the membrane wound, in order to facilitate the constriction of the hole by ANXA6." (PMID 35207075, 2022). "Conversely, there are several studies demonstrating involvement of other types of annexins, such as annexins A1 and 2, in proliferation of other types of cancer cells; therefore, this growth-activating property of ANXA4 might be a common feature among annexins." (PMID 24244679, 2013). "Additionally, many studies have reported a relationship between ANXA4 expression and cancer." (PMID 22970268, 2012). "Five different proteins identified were serum albumin, Heat shock protein 27, gamma actin, squamous cell carcinoma 1 (SCCA-1), and ANXA4 when compared to the control sample." (PMID 34181340, 2021). "Several reports from other cancers showed that patients with high GLUD1, ANXA4, and PLXDC1 expression have low overall survival, but our findings in CCA are contrasting." (PMID 33193605, 2020). "MSKE also prompted the down-regulation of antiapoptotic and survival proteins, such as annexin A4 (ANXA4), a member of the Ca2+-regulated and phospholipid-binding annexin superfamily, which is regularly increased in many cancer types." (PMID 30453669, 2018).
cancer (continued). "For the first time, our paper describes EIF4A1, CLIC1, PRDX6, CLIC4, ENO1, ANXA4, EMD and Ku70 in relation to EEC, although their role is well established in other cancers." (PMID 22415234, 2012). "The epithelial and cancer cells showed higher KRT8, KRT18, KRT19 and ANXA4 expression." (PMID 39149248, 2024). "Thus, ANXA4 and ANXA6 improve cells' ability to cope with stress-induced plasma membrane disruptions, which appears to be a strategy used by cancer cells to counteract frequent membrane injuries." (PMID 29158488, 2017). "Among these new candidates, Annexin A4 (ANXA4) had been reported to play a role in drug resistance, with its expression increased in clones resistant to paclitaxel, a drug commonly used in the treatment of cancer patients." (PMID 24223161, 2013). "Conversely, all three poorly or undifferentiated carcinomas and 13 of 14 SC expressed no detectable ANXA4." (PMID 24244679, 2013). "However, the potential correlation between SNO of ANXA4 and the cancer mechanism has not been reported." (PMID 37124724, 2023). "Not only because many studies indicated that NF-κB activation is involved in cancer drug-resistance, but also studies have indicated that other ANX family member (ANXA4) could interact with the NF-κB subunit, and ANXA2 has a similar conserved structure domain with ANXA4." (PMID 28814318, 2017). "Notably, MCF7A4−CRISPR cells appeared to compensate from lack of ANXA4 by upregulating their ANXA6 protein expression, suggesting that MCF7 cancer cells require at least one of these proteins to counteract plasma membrane damage." (PMID 29158488, 2017). "Whether the overall mode of action of ANXA4 (membrane curvature) and ANXA6 (membrane constriction) is similar in cancer and skeletal muscle cells or not, the mechanism would be slightly different, with an ANXA4-induced inward versus outward curvature, respectively." (PMID 35207075, 2022).